IL37 (interleukin 37)
Diseases named in the same sentence as IL37 in open-access papers (continued):
Sharing a sentence is not in itself a finding about the gene and the disease.
colitis (continued). "The co-cited reference entitled “Interleukin 37 expression protects mice from colitis” with high betweenness centrality (0.21) could be identified as a vital point that provides important bridging connections between two research interests." (PMID 35935954, 2022). "Thus, our data corroborated these concepts, demonstrating that IL-37 promotes the pathology of colitis depending on microbiota dysbiosis, and future studies into the interaction of host and microbiota composition need to consider the environmental changes." (PMID 35836813, 2022). "Furthermore, extended analysis at the species level demonstrated that IL-37 mainly increased the abundance of Escherichia coli (E. coli), a common pathogenic strain of the gut microbiota dysbiosis in DSS-induced colitis." (PMID 35836813, 2022). "The detrimental role of IL-37 in conventionally housed colitis mice depends on their intestinal microbiota composition, which is characterized by intestinal epithelial barrier impairment, the infiltration of neutrophils and NK cells, and the upregulation of proinflammatory cytokines." (PMID 35836813, 2022). "We thus sought to investigate whether IL-37 accelerated DSS-inflamed colitis results from intestinal epithelium barrier disorders and functional disruption." (PMID 35836813, 2022). "It has been proved that IL-37 has therapeutic effects on tumors, colitis, and rheumatoid arthritis." (PMID 36418383, 2022). "Although IL-37 can protect against DSS-induced colitis under SPF circumstances 20, 21, whether environmental conditions and specific microbial communities influence the immunoregulatory function of IL-37 in IBD remains unknown." (PMID 35836813, 2022). "Moreover, there are several similar observations that IL-37 restricted the local inflammatory responses by inhibiting recruitment of inflammatory cells in colitis, liver inflammatory injury, and psoriasis." (PMID 34471467, 2021). "In addition, transgenic IL-37 mice are protected from several disease models, including LPS-induced septic shock, dextran sulfate-induced colitis, concanavalin A-induced hepatitis, and cerebral ischemia/reperfusion injury." (PMID 34471467, 2021). "Previous studies revealed that mice expressing human IL-37 are protected from acute DSS colitis." (PMID 31781119, 2019). "Similarly, the protein levels for IL-37 were almost undetectable in the IL-37+/+ control group but were increased after the treatment of DSS-induced colitis." (PMID 30563054, 2018). "In the present study, we investigated the role of IL-37 with a transgenic mouse strain that expresses human IL-37 in a murine model of colitis resulting from repeated cycles of dextran sodium sulfate (DSS) administration that mimics the relapsing nature of the IBD." (PMID 30563054, 2018). "Animal studies demonstrate anti-inflammatory roles of IL-37 in colitis." (PMID 28420941, 2017). "And the transgenic mice with IL-37 overexpression showed more resistance to DSS induced colitis." (PMID 28467774, 2017). "Interestingly, wild-type (WT) mice reconstituted with bone marrow from IL-37tg mice were also protected from DSS-induced colitis, indicating that hematopoietic IL-37 expression is sufficient for this protective effect." (PMID 28792474, 2017). "Therefore, these experiments indicated that the deterioration of the intestinal epithelium barrier induced by IL-37 in DSS-induced colitis under conventional housing circumstances involves the downregulation of IL-1β and IFN-γ expression, which is dependent on NF-κB signaling." (PMID 35836813, 2022). "Therefore, we examined whether IL-37-producing T-cells could improve the colitis activity in our DSS-induced mouse model." (PMID 30563054, 2018). "Finally, although little is currently known regarding the potential contribution of IL-36 family members in GI inflammation/homeostasis, another IL-1 family member, IL-37, is emerging as a potent anti-inflammatory cytokine with the ability to down-regulate colitis." (PMID 23847622, 2013).
colitis (continued). "Mice ectopically expressing human IL-37 show reduced epithelial damage and inflammation after DSS-induced colitis." (PMID 37799712, 2023). "Since the mechanism of immune cell crosstalk is a great enigma, it will be fascinating to determine how IL-37 modulates the interaction of NK cells and neutrophils in this experiment and whether blocking these inflammatory signals can protect against IL-37tg mouse colitis." (PMID 35836813, 2022). "Anti-inflammatory effects of IL37, a newer member of the IL1 family, were described in a mouse model: Transgenic mice expressing IL37 were protected from colitis." (PMID 33861738, 2021). "In addition, IL-37 in vivo could inhibit NLRP3 activation also in colitis- and LPS-induced disease." (PMID 32849879, 2020). "Human IL-37 transgenic mice are protected against metabolic syndrome, systemic inflammation reaction, DSS-induced colitis, and acute myocardial infarction." (PMID 32849879, 2020). "IL-37 has been reported to be protective against septic shock, DSS-induced colitis, concanavalin A-induced hepatitis, and in an experimental model of ischemia/reperfusion (I/R)-induced hepatitis." (PMID 24788826, 2014). "IL-37 also displays an anti-inflammatory role within the epithelium, as shown in experiments on T84 colonic carcinoma cells, human and murine intestinal organoids, and dextran sodium sulfate (DSS)-colitis mice." (PMID 37799712, 2023). "We demonstrate that the transgenic expression of human IL-37 promotes DSS-induced colitis under conventional housing conditions but not under SPF conditions." (PMID 35836813, 2022). "Moreover, under this experimental setting, events of IEC apoptosis were observed in IL-37tg colitis mice, indicating that IEC apoptosis is a feature of IL-37-promoted intestinal epithelial barrier dysfunction." (PMID 35836813, 2022). "An antibody to the IL-10 receptor did also not counteract the effect of IL-37 in the model of acute DSS-induced colitis." (PMID 31781119, 2019). "Although the increased release of IL-10 is observed mediated by human IL-37 (hIL-37) in ex vivo colonic explant tissues from dextran sodium sulfate (DSS)-induced mouse model of colitis, the protective function of IL-37 is not affected by the IL-10-receptor antibody blockade." (PMID 37928545, 2023). "Studies performed in IL‐37 transgenic (IL‐37tg) mice reveal that IL‐37 potently suppresses IL‐6, IL‐1β, and TNF‐α production in response to various TLR agonists or diseases driven by chronic inflammation including atherosclerosis, hepatocellular carcinoma, and colitis." (PMID 33480151, 2021).
atherosclerosis (44 papers, 2014 to 2025). A disease characterized by the build-up of fatty material and calcium deposition in the arterial wall resulting in partial or complete occlusion of the arterial lumen. "IL-18 is linked to plaque instability in atherosclerosis, while IL-37 exhibits anti-inflammatory properties." (PMID 37637634, 2023). "Recombinant IL- (rIL-) 37 has been shown to alleviate mouse atherosclerosis and myocardial infarction by inhibiting cardiomyocyte apoptosis, a finding that asserts that IL-37 is inextricably linked to cardiovascular disease." (PMID 35602104, 2022). "Then, ApoE−/− mice were treated with a recombinant human IL-37 protein to investigate the association of IL-37 with innate and adaptive immunity in the development of atherosclerosis." (PMID 28607385, 2017). "We previously reported a possible strong association between IL-37 and atherosclerosis as discovering IL-37 in the foam-like cells of carotid artery plagues in rabbits." (PMID 28039466, 2017). "This transcriptome enriches key AD pathways more than the individual studies, and associates AD with novel pathways, such as atherosclerosis signaling (IL-37, selectin E/SELE)." (PMID 26459294, 2015). "As DCs have been implicated in atherosclerosis pathogenesis, we investigate whether IL-37 could be used for the establishment of tDCs from patients with ACS." (PMID 31686988, 2019). "As IL-37 is involved in anti-inflammation, reduced expression of IL-37 associated with SNP rs3811047 as found in this study may cause inflammation, increasing risk of atherosclerosis and CAD." (PMID 28181534, 2017). "Given that IL-37 may be associated with the development of atherosclerosis, we hypothesize that IL-37 may play a potential role in the inflammation response including plasma and leukocytes in AMI patients after PCI." (PMID 25960620, 2015). "However, the underlying mechanism, by which IL-37 attenuates the symptom of atherosclerosis, remains unclear." (PMID 28039466, 2017). "While the role of IL-37 in atherosclerosis is well established, its involvement in macrophage ferroptosis and its potential as a therapeutic target in cardiovascular diseases represent emerging areas of interest." (PMID 39337246, 2024). "This classification is supported by findings demonstrating that IL-37 mitigates the progression of atherosclerosis in an in vivo IL-37 transgenic animal model." (PMID 38312834, 2024). "Further mechanistic studies, such as those involving the administration of exogenous IL-37 (e.g., recombinant human IL-37 or IL-37 transgenic mice), are necessary to elucidate the precise role of IL-37 in atherosclerosis." (PMID 39337246, 2024). "The upregulation of IL-10 expression and concomitant reduction in TNF and IL-18 production were identified as direct immunoregulatory mechanisms through which IL-37 ameliorated atherosclerosis and coronary artery calcification." (PMID 39337246, 2024). "In patients with atherosclerosis, higher IL-37 levels have been detected in calcified samples, particularly within macrophages and vascular smooth muscle cells." (PMID 39337246, 2024). "This review aims to fill this gap by summarizing existing knowledge on interleukin-37, including its regulatory functions and impact on ferroptosis in conditions such as atherosclerosis and myocardial infarction." (PMID 39337246, 2024). "The reference with the strongest burst (8.06) demonstrated that IL-37 protects against the development of atherosclerosis in ApoE-/- mice by eliminating the maturation of DCs." (PMID 35935954, 2022). "IL-37 plays a definite antiinflammatory role in multiple inflammatory and metabolic disorders, such as diabetes, atherosclerosis, and inflammatory bowel disease." (PMID 36166295, 2022). "In inflammatory diseases, increased levels of endogenous IL-37 protein have a protective effect on the body, with the ability to suppress inflammation in gout, atherosclerosis and chronic periodontitis." (PMID 36002836, 2022).
atherosclerosis (continued). "IL-37 has recently been considered to enhance Treg abundance and the production of anti-inflammatory cytokines in patients with atherosclerosis and acute coronary syndrome." (PMID 35935954, 2022). "A previous study showed that in vessels with atherosclerosis and arterial calcification, IL-37 was predominantly expressed in SMCs and that its expression was significantly higher in the arteries than in the other tissues." (PMID 35602104, 2022). "Interleukin 37 (IL-37) is an anti-inflammatory cytokine expressed in foam cells located in the atherosclerosis plaques." (PMID 34199391, 2021). "Elevated IL-37 expression has also been observed in a murine model of atherosclerosis as well as in plasma from acute coronary syndrome patients." (PMID 34422917, 2021). "Continued research is necessary to answer the question of the relationship between pro-and anti-inflammatory cytokines, IL-37, and vitamin D status in the pathogenesis of atherosclerosis, neointima formation, and restenosis." (PMID 34445530, 2021). "IL-37 was a new antiatherogenic inflammatory cytokine and had strong anti-inflammatory properties and was a protective role in atherosclerosis." (PMID 33029103, 2020). "IL-35 is induced by proinflammatory stimulation and the early development of atherosclerosis and can inhibit endothelial cell activation, while IL-37 and IL-10 also play immunosuppressive roles as anti-inflammatory factors." (PMID 32733941, 2020). "IL-37 was a new antiatherogenic inflammatory cytokine and played the strong atheroprotective and anti-inflammatory roles in atherosclerosis." (PMID 33029103, 2020). "It has been reported that IL-37 can promote macrophage polarization from the pro-inflammatory subtype (M1) to the anti-inflammatory subtype (M2) in atherosclerosis." (PMID 31736917, 2019). "Currently, a growing bodies of research have revealed the view that IL-37 plays a vital role to inhibit various inflammation responses especially in the formation of atherosclerosis in cardiovascular disease." (PMID 30728750, 2019). "Myocardial infarction a similarly debilitating cardiovascular disorder like atherosclerosis is equally ameliorated by IL-37." (PMID 29641433, 2018). "IL-37 was reported to ameliorate symptoms of atherosclerosis and arterial calcification via its influence on BMP-2 mediated ALP expression." (PMID 29641433, 2018). "IL-37 is proposed to resolve atherosclerosis by modulating macrophage polarity and decreasing the effective size of an aortic plaque in relation to surrounding vascular cavity." (PMID 29641433, 2018). "Upregulation of IL-10 expression with a concomitant decrease in the production of TNF-α and IL-18 was put forward as a direct anti-inflammatory mechanism of IL-37 mediated amelioration of atherosclerosis and CAC." (PMID 29641433, 2018). "In order to assess the role of IL-10 in IL-37–mediated protection from atherosclerosis, we administered IL-37 or PBS together with anti-IL-10R mAb or isotype antibody." (PMID 28607385, 2017). "Using a diabetic model, we found that recombinant human IL-37 attenuated both atherosclerosis and vascular calcification via regulating the production of osteoprotegerin and inflammatory cytokines such as IL-10, IL-18, TNF-α and IFN-γ17." (PMID 28607385, 2017). "The results from ELISA and RT-PCR examinations also supported the immunoregulatory properties of IL-37 in atherosclerosis." (PMID 28607385, 2017). "To investigate the role of IL-37 in protecting against atherosclerosis, we detected the atherosclerosis lesion sizes between the IL-37 group and the control group." (PMID 28607385, 2017). "IL‐37 can modulate the maturation of DC 30, suggesting its protective effect on atherosclerosis via influencing DC." (PMID 28548248, 2017). "In the present study we investigated the effect of hematopoietic expression of IL-37 on atherosclerosis development under low-grade inflammatory conditions." (PMID 28792474, 2017).
atherosclerosis (continued). "To investigate the effect of IL-37 on atherosclerosis, we treated ApoE−/− mice with recombinant human IL-37 protein." (PMID 28607385, 2017). "We previously reported that the plasma level and expression of IL-37 of the plaque are significantly increased in the pathogenesis of atherosclerosis, a chronic inflammatory process." (PMID 28039466, 2017). "The results showed that the atherosclerosis lesion size in the aortic sinus of the IL-37 group was significantly decreased compared to that of the control group (3.22 ± 0.16 × 105 μm2 versus 4.46 ± 0.17 × 105 μm2, P < 0.01)." (PMID 28607385, 2017). "This is further supported by a recent study in which systemic IL-37 treatment protected from atherosclerosis via modulating immune cell responses." (PMID 28792474, 2017). "It is demonstrated that IL‐37 ameliorated inflammatory responses in epithelial cells, macrophages, and dendritic cells, indicating its potential role in atherosclerosis." (PMID 28548248, 2017). "Previously, we discovered that the rosuvastatin treatment dramatically lowered the IL-37 level in rabbits with atherosclerosis, a chronic inflammatory process." (PMID 28039466, 2017). "Our transcriptome is the first association of AD genomic fingerprinting with the atherosclerosis signaling pathway, which includes genes associated with vascular inflammation (SELE, IL-37, S100A8)." (PMID 26459294, 2015). "Since IL-37 is not found in mice, exogenous IL-37 (e.g., recombinant human interleukin-37) and endogenous IL-37 model (e.g., IL-37 transgenic mice) can be used to clarify the role of IL-37 in atherosclerosis." (PMID 24733959, 2014). "Recently, unpublished evidence showed that IL-37 was expressed in the foam-like cells of atherosclerotic coronary and carotid artery plaques, suggesting that IL-37 is involved in atherosclerosis-related diseases." (PMID 24733959, 2014). "Consequently, IL-37 emerges as a promising immunoregulatory cytokine with significant potential in the context of atherosclerosis, particularly as an inflammation inhibitor that can shift the cytokine balance away from excessive inflammation." (PMID 39337246, 2024). "However, the exact role of altered IL-37 levels in the progression of atherosclerosis and the onset of ACS is still not fully understood." (PMID 39337246, 2024). "Furthermore, the recently discovered IL-37, an emerging anti-inflammatory cytokine, exhibits intriguing potential in the context of atherosclerosis." (PMID 37637634, 2023). "Consequently, there is active research looking at the potential role of IL-37 in fighting several types of inflammatory diseases, including atherosclerosis." (PMID 36613465, 2022). "Targeting specific inflammatory pathways that are overrepresented in atherosclerosis or potentiating immunomodulatory cytokines—such as IL-37—might help accomplish this long-awaited goal." (PMID 36613465, 2022). "In addition, macrophage-specific IL-37 expression led to reduced plaque development and decreased systemic inflammation in atherosclerosis-prone mice." (PMID 36613465, 2022). "It has been anteriorly described that the expression of IL-37 is involved in the pathogenesis of atherosclerosis and that this biomarker has an inflammatory effect by reducing the expression of other inflammatory cytokines, such as interleukin-18 (IL-18) and TNF-α." (PMID 36012430, 2022). "In addition, it has been well-reviewed that IL-37 substantially reduces the development of atherosclerosis, which has been confirmed in an IL-37 transgenic animal model." (PMID 35186997, 2022). "In addition, IL-37 substantially reduces the development of atherosclerosis in an IL-37 transgenic animal model." (PMID 34513891, 2021).